CTRC (chymotrypsin C)
Description:
Regulates activation and degradation of trypsinogens and procarboxypeptidases by targeting specific cleavage sites within their zymogen precursors. Has chymotrypsin-type protease activity and hypocalcemic activity.
Synonyms: CLCR; ELA4
Tractability: Small molecule: a high-quality ligand is known; it belongs to a druggable protein family. Antibody: UniProt predicts a signal peptide or a membrane-spanning region. PROTAC: a small molecule that binds it is known.
Target class: Serine protease; Enzyme; Serine protease PA clan; Serine protease S1A subfamily; Protease
Gene: Protein-coding gene on chromosome 1 (15,438,442 to 15,449,242, forward strand). Ensembl gene ENSG00000162438.
Pathways (Reactome):
Developmental Biology: Developmental Lineage of Pancreatic Acinar Cells
Gene Ontology:
Molecular function: peptidase activity; protein binding; serine-type endopeptidase activity
Biological process: intracellular calcium ion homeostasis; proteolysis
Genetic constraint (gnomAD): Loss-of-function variants: 32 observed, 37.48 expected, observed/expected ratio (o/e) 0.85, 90% interval 0.64 to 1.15. The synonymous counts are far from expectation, so gnomAD's model fits this gene poorly and the ratio says little. Missense variants: 324 observed, 377.31 expected, observed/expected ratio (o/e) 0.86, 90% interval 0.78 to 0.94. Synonymous variants: 119 observed, 154.63 expected, observed/expected ratio (o/e) 0.77, 90% interval 0.66 to 0.9.
Homologues: Orthologues: chimpanzee CTRC (99% identical), pig CTRC (85% identical), rabbit CTRC (82% identical), guinea pig CTRC (76% identical), rat Ctrc (76% identical), Drosophila melanogaster CG11912 (29% identical). Paralogues in human: CTRB2 (40% identical), CTRB1 (40% identical).
Diseases named in the same sentence as CTRC in open-access papers:
CTRC is named in the same sentence as 25 diseases in open-access papers, as found by Europe PMC text mining. Sharing a sentence is not in itself a finding about the gene and the disease. The quoted sentences say what the papers report.
pancreatitis (41 papers, 2011 to 2025). Inflammation of the pancreas. "Loss-of-function mutations in CTRC impair this protective mechanism, increasing susceptibility to pancreatitis." (PMID 40427173, 2025). "The protective effect of chymotrypsins against pancreatitis was first discovered by human genetic studies that investigated association of CTRC mutations and chronic pancreatitis." (PMID 32678161, 2020). "Human genetic studies revealed that loss-of-function mutations in CTRC impair protective trypsinogen degradation and increase pancreatitis risk significantly." (PMID 32678161, 2020). "This notion is also supported by the genetic evidence that mutations in cationic trypsinogen (PRSS1), pancreatic secretory trypsin inhibitor (SPINK1), and chymotrypsinogen C (CTRC) are associated with the susceptibility of pancreatitis." (PMID 25140315, 2014). "CTRC (chymotrypsin C) encodes a protein crucial for regulating the activation and degradation of trypsinogen and procarboxypeptidase, protecting the pancreas from pancreatitis and influencing pain progression in chronic pancreatitis." (PMID 41132793, 2025). "Because CFTR mutations are not necessarily correlated with the onset of pancreatitis, PRSS1, SPINK1 and CTRC mutations may also lead to pancreatitis." (PMID 36835437, 2023). "In recent years, molecular studies have allowed us to identify mutations of key genes, including the CTRC gene, which might be crucial in the development of pancreatitis." (PMID 28095786, 2017). "In CF, the CTRC gene protects against harmful trypsinogen activation, protecting against pancreatitis." (PMID 41158431, 2025). "Normally, trypsin activity is inhibited by the serine protease inhibitor Kazal type 1 (SPINK1) and further regulated by breakdown through chymotrypsin C (CTRC) and cathepsin L. However, a failure in this protective mechanism can lead to pancreatitis." (PMID 41378273, 2025). "Individuals who underwent germline multigene testing for pancreatitis susceptibility genes (CASR, CFTR, CPA1, CTRC, PRSS1, SPINK1) through a large commercial laboratory between 2017 and 2022 were included." (PMID 39172977, 2024). "PRSS1, serine peptidase inhibitor Kazal type 1 and chymotrypsin C are specifically or highly expressed in the acinar cells of a patient with pancreatitis." (PMID 37682188, 2023). "Chymotrypsin C normally degrades trypsinogen limiting; therefore, its intrapancreatic activation and protection against pancreatitis." (PMID 36977272, 2023). "The novel mutations mapped in LPL, CFTR, CTRC, and PHKB genes show a potential for new finding in pancreatitis and their clinical-genetic importance for diagnostic and pharmaceutics." (PMID 37603299, 2023). "Mutations in PRSS1, SPINK1, CTRC, CASR, and CFTR were linked with pancreatitis and pancreatic cancers when the molecular basis of pancreatitis was investigated." (PMID 36434531, 2022). "The digestive protease chymotrypsin C (CTRC) protects the pancreas against pancreatitis by degrading potentially harmful trypsinogen." (PMID 35594281, 2022). "At least five genes have been identified to be associated with pancreatitis: serine protease 1 (PRSS1), serine peptidase inhibitor Kazal type 1 (SPINK1), CFTR, chymotrypsin C (CTRC), and calcium sensing receptor (CASR)." (PMID 35844741, 2022). "Germline testing, currently for recommended etiologic mutations associated with pancreatitis, includes evaluation for pathogenic variants in the CEL, CFTR, CPA1, CTRC, PRSS1, and SPINK1 genes in symptomatic individuals." (PMID 33375361, 2020). "The mechanisms by which CTRC protects against pancreatitis have been established; however, the importance of CTRC variants in terms of risk for RAP and CP is less clear." (PMID 26100556, 2015). "Mutations in other genes such as anionic trypsinogen (PRSS2), the serine protease inhibitor Kazal type 1 (SPINK1), CFTR, chymotrypsinogen C (CTRC) and calcium-sensing receptor (CASR) are also associated with an increased risk for pancreatitis." (PMID 22133269, 2011).
pancreatitis (continued). "Mutations in CTRC (chymotrypsinogen C) and CFTR (cystic fibrosis transmembrane receptor) have also been associated with increased risk for pancreatitis." (PMID 22216129, 2011). "We investigated the expression of pancreatitis-associated genes with the ability to act as positive regulators of the IL-6 amplifier; these genes include GGT1, PRSS1, CASR, CTRB1, ABO, SPINK1, and CTRC." (PMID 38806529, 2024). "Interestingly, we found no mutations that passed quality control or the expected segregation pattern, in genes known to be associated with pancreatitis such as PRSS1, CFTR, SPINK, CPA1, CTRC, CLDN2, and PLINP." (PMID 36699452, 2022). "In the following years, loss-of-function variants in the pancreatic secretory trypsin inhibitor (SPINK1), calcium-sensing receptor (CASR) and chymotrypsinogen C (CTRC) genes, firmly established the pivotal role of prematurely activated trypsin within the pancreas in the etiology of pancreatitis." (PMID 30134826, 2018). "Indeed, mutant variants in CTRC and SPINK1 genes are known to contribute to pancreatitis susceptibility." (PMID 24795752, 2014). "The aetiology of paediatric pancreatitis, which includes infections, systemic diseases, trauma, drug induction, biliary system diseases, anatomical abnormalities and genetic cause (CFTR, PRSS1, SPINK1, CTRC mutations), is significantly different from that of adults." (PMID 34178894, 2021). "So far, several genes with potential application in the diagnosis of pancreatitis have been described, including PRSS1, CFTR, CTRC, and SPINK1." (PMID 39457082, 2024). "The patient did not have known pancreatitis-associated mutations, such as PRSS1, SPINK1, CTRC, CPA1, or TRPV6." (PMID 36419930, 2022). "In contrast to the demonstrated protective effects of CTRB1 and CTRC in mice against pancreatitis, the observations reported here did not indicate a similar role for CTRL." (PMID 32678161, 2020). "Thus, relative to CTRC, the contribution of CTRB1 and CTRB2 to the chymotrypsin-dependent protection against pancreatitis in humans seems limited." (PMID 32678161, 2020). "CP might cluster in families, and in many of these affected subjects as well as young patients without a family history of pancreatitis, mutations in the genes coding for cationic trypsinogen (PRSS1), pancreatic secretory trypsin inhibitor (SPINK1) and chymotrypsinogen C (CTRC) can be identified." (PMID 24260417, 2013).
chronic pancreatitis (20 papers, 2010 to 2025). A chronic inflammatory process causing damage and fibrosis of the pancreatic parenchyma. "The altered protease activity of chymotrypsin C revealed that it can be a risk factor for chronic pancreatitis, a role that is described in detail in Section 3.3." (PMID 34436220, 2021). "Of the 25 patients, 18 (72%) of them were found to have a known genetic mutation (PRSS1, SPINK1, CFTR, CTRC) as the etiology for acute recurrent or chronic pancreatitis." (PMID 33925523, 2021). "Mutations in genes encoding cationic trypsinogen (PRSS1), pancreatic secretory trypsin inhibitor (SPINK1) and chymotrypsinogen C (CTRC) are associated with chronic pancreatitis." (PMID 24260417, 2013). "Pathogenic mutations or variants in the CTRC gene cause loss of function, affecting secretion and proteolytic stability, and secretion increases the risk of chronic pancreatitis, whereby oxidative stress is a major contributor to the inflammation and fibrosis observed in the pancreas." (PMID 41158431, 2025). "Thus, loss-of-function mutations in CTRC can cause a decrease in the catalytic activity of CTRC and impaired trypsinogen degradation, which are causative risk factors for chronic pancreatitis." (PMID 34436220, 2021). "Recurrent variants of the PRSS1, SPINK1, CTRC, CFTR, and CPA1 genes, contributing to the genetic predisposition to chronic pancreatitis development were identified in a cohort of Russian patients." (PMID 37389024, 2023). "The aim of the study was to determine the structure of chronic pancreatitis genetic causes in patients living in the European part of Russia by sequencing the entire coding sequence of the PRSS1, SPINK1, CTRC, CFTR, and CPA1 genes." (PMID 37389024, 2023). "PVs in two genes that are associated with AD chronic pancreatitis-PRSS1 (OMIM #276000; PV-rs111033565) and CTRC (OMIM #601405; PV-rs202058123) were detected." (PMID 37107695, 2023). "Hereditary pancreatitis can be defined as a patient with recurrent acute or chronic pancreatitis who has a first or second degree relative having similar presentation or one who presents with mutated SPINK1, PRSS1, CFTR, and CTRC genes." (PMID 31588422, 2019). "Rare pathogenic variants in the SPINK1, PRSS1, CTRC, and CFTR genes have been strongly associated with a risk of developing chronic pancreatitis (CP)." (PMID 30420730, 2018). "The developed genetic panel (PRSS1, SPINK1, CTRC, CFTR, and CPA1 genes) for identification of genetic risk factors of the chronic pancreatitis development and the usage of the next-generation sequencing technology allowed to specify genetic predictors of the disease development in 61% of patients." (PMID 37389024, 2023). "Given that in the pancreas, PRSS1, SPINK1 and CTRC are expressed exclusively in the acinar cells, these genetic findings suggested an important role for prematurely activated trypsinogen within the pancreatic acini in initiating chronic pancreatitis." (PMID 23951356, 2013). "Chronic pancreatitis has also been associated with mutations in other genes such as SPINK 1 (serine protease inhibitor Kazal Type I), CFTR (Cystic Fibrosis transmembrane conductance regulator), CTRC (chymotrypsin C)." (PMID 20950468, 2010).
pancreatic cancer (7 papers, 2019 to 2025). "Additionally, chymotrypsin C in humans has also been implicated in pancreatic cancer, and the orthologue in zebrafish, ela2l was upregulated in the short-term duration exposure for both 4-nonylphenol at 10 nM and triclosan at 10 nM." (PMID 35202241, 2022). "A few studies about proteomics showed downregulated CTRB2, CELA3A, and CTRC, in pancreatic cancer, similar to the results of our study." (PMID 40289610, 2025). "Pancreatic cancer cells express around 20% of chymotrypsin C normal cells expression, with this enzyme participating in cancer cell apoptosis and migration." (PMID 37296850, 2023).
acute pancreatitis (6 papers, 2014 to 2024). An acute inflammatory process that leads to necrosis of the pancreatic parenchyma. "The aim of this study was to determine the frequency of genetic mutations in SPINK1, CFTR and CTRC genes in patients with acute pancreatitis (AP), as well as to investigate their relation with the etiology and clinical course." (PMID 26100556, 2015).
hereditary pancreatitis (5 papers, 2010 to 2022). "These genes are either associated with non-life-threatening disorders (FLG; ichthyosis vulgaris), late-onset disorders (NOTCH3; cerebral autosomal dominant arteriopathy with sub-cortical infarcts and leukoencephalopathy, CADASIL) or risk factors for disease (PRSS1, CTRC; hereditary pancreatitis)." (PMID 36335097, 2022).
cholangiocarcinoma (1 paper, 2015). A carcinoma that arises from the intrahepatic biliary tree (intrahepatic cholangiocarcinoma) or from the junction, or adjacent to the junction, of the right and left hepatic ducts (hilar cholangiocarcinoma). "Nine proteins (3%) were identified as less abundant in cholangiocarcinoma, which included pro-activator polypeptide isoform a pre-pro-protein, carboxypeptidase B, chymotrypsin-like elastase family member 2A, chymotrypsin like elastase family member 3B, and chymotrypsin-C." (PMID 25304323, 2015).
COVID-19 (1 paper, 2025). A disease caused by infection with severe acute respiratory syndrome coronavirus 2. "Interestingly, we found early levels of TRAIL-R2, TNFRSF11A, and CTRC to be statistically elevated in subjects who would die from COVID-19 complications." (PMID 40424310, 2025).
emphysema (1 paper, 2025). "Importantly, studies on animal models indicate that unrestrained trypsin activity can also lead to emphysema, and thus a decrease in CTRC expression might be relevant for the development of emphysema in patients with COPD." (PMID 40343765, 2025).
malnutrition (1 paper, 2016). Inadequate nutrition resulting from poor diet, malabsorption, or abnormal nutrient distribution. "Genetic susceptibility due to genetic mutations particularly in SPINK1, CFTR, CTRC, and CLDN2/MORC4 genes is the most important factor and not malnutrition or dietary toxins for idiopathic CP suggesting the term ‘tropical pancreatitis’ is a misnomer." (PMID 29868209, 2016).
cancer (5 papers, 2012 to 2025). A tumor composed of atypical neoplastic, often pleomorphic cells that invade other tissues. "Conversely, overexpression of a mutant chymotrypsin C lacking the N-glycosylation in the protease domain caused ER stress in cancer cells (Bence and Sahin-Tóth, 2011)." (PMID 29889025, 2018).
CTRC also shares sentences with these, for which no sentence is quoted: tumor (4 papers); hematologic malignancy (2); hypertriglyceridemia (2); Sepsis (2); CADASIL (1); diabetes (1); ichthyosis vulgaris (1); insulinoma (1); invasive candidiasis (1); Leukoencephalopathy (1); lipodystrophies (1); myocardial infarction (1); neutropenia (1); pancreatic disease (1); urinary tract infection (1).